SMAD3 (SMAD family member 3)
Diseases named in the same sentence as SMAD3 in open-access papers (continued):
Sharing a sentence is not in itself a finding about the gene and the disease.
syringomyelia (1 paper, 2023). Syringomyelia is characterized by cerebrospinal fluid (CSF)-filled cavities (syrinx) inside the spinal cord, either as a result of a known cause (secondary syringomyelia, SS) or, more rarely, due to an unknown cause (primary syringomyelia, PS). "To confirm the role of the TGFβR-Smad3 axis on protrusion and syrinx formation, we injected DMSO and SIS3, a Smad3 inhibitor, into rats with syringomyelia by intraperitoneal injection respectively in vivo." (PMID 37248485, 2023). "Activation of TGFβR-Smad3 pathway and knockdown/knockout of TGFβR or Smad3 by using more syringomyelia animal models would be helpful for detection of the syrinx enlargement under syringomyelia in the future experiments." (PMID 37248485, 2023).
T-cell leukemia (1 paper, 2021). A malignant disease of the T-lymphocytes in the bone marrow, thymus, and/or blood. "In adult T-cell leukemia cells infected with HTLV-1, virus oncoprotein Tax inhibits TGF-β signaling by reducing the SMAD3 DNA binding activity." (PMID 33546553, 2021).
tendon disease (1 paper, 2024). "Here,a new LNP platform for simultaneous delivery of SMAD3 siRNAand COL1A1 mRNA was developed by using microfluidics technology asa potential therapeutic approach for treating tendinopathy." (PMID 39144399, 2024).
thoracic cancer (1 paper, 2018). A primary or metastatic malignant neoplasm affecting the tissues of the thorax. "Additionally, JQ1 suppressed BRD4, c-MYC, Collagen I, TGF-β, p-NF-κB p65, p-Smad2 and p-Smad3 expressions after irradiation, repressed proliferation and transdifferentiation of lung fibroblasts, and impaired clonogenic survival of thoracic cancer cells." (PMID 29343723, 2018).
uremia (1 paper, 2019). A clinical syndrome associated with the retention of renal waste products or uremic toxins in the blood. "Activation of downstream TGF-β/Smad signaling pathway in this experimental setting was confirmed by the markedly increased gene expression of Smad3 and phospho-Smad3 isoforms observed in the PM of animals with PF, particularly in the group of PF with uremia." (PMID 31455237, 2019).
uterine tumors (1 paper, 2023). "We profiled the data from uterine tumors deposited to the cBioPortal of Cancer Genomics for mutations of the TGFβ signaling pathway and identified several mutations in TGFβ-related receptors (TGFBR1, TGFBR2, ACVR1B, ACVR1C, ACVR2A, ACVR2B) and transcription factors (SMAD2, SMAD3, SMAD4)." (PMID 36906706, 2023).
vitamin D deficiency (1 paper, 2019). A nutritional condition produced by a deficiency of VITAMIN D in the diet, insufficient production of vitamin D in the skin, inadequate absorption of vitamin D from the diet, or abnormal conversion of vitamin D to its bioactive metabolites. "The effects of vitamin D deficiency on BLM-induced activation of TGF-β/Smad3 signaling were then analyzed." (PMID 31775746, 2019). "Moreover, vitamin D deficiency aggravated BLM-induced pulmonary Smad3 phosphorylation." (PMID 31775746, 2019).
vitiligo (1 paper, 2021). Generalized well circumscribed patches of leukoderma that are generally distributed over symmetric body locations and is due to autoimmune destruction of melanocytes. "As the results shown that the expression of ANKRD6, ATG13, SEMA4D, SMAD3, and PAXILLIN were all significantly downregulated in vitiligo." (PMID 33968138, 2021). "Furthermore, we detected the expression of target genes such ANKRD6, ATG13, SEMA4D, SMAD3, and PAXILLIN to verify that these circRNA-ceRNA networks are involved in the pathological process of vitiligo." (PMID 33968138, 2021). "Therefore, we obtained the circRNA-ceRNA networks that might have the important roles in vitiligo pathology: hsa_circ_0007716 – hsa-miR-149-5p – ATG13/SEMA4D, hsa_circ_0003770 –hsa-miR-320a-3p – SMAD3 and hsa_circ_0087961 – hsa-miR-27a-3p - PAXILLIN." (PMID 33968138, 2021).
ZIKV infection (1 paper, 2020). "In vitro, we found that ZIKV infection reduced Foxp3 expression in EL‐4 cells, as well as Smad4 in addition to the reduced phosphorylation of Smad2 and Smad3." (PMID 32057179, 2020). "ZIKV infection did not affect Smad2 and Smad3 expression, but significantly down‐regulated Smad4 expression as well as P‐Smad2 and P‐Smad3 (P < .05)." (PMID 32057179, 2020). "However, compared to ZIKV infection in mock transfection (no Smad2 overexpression), overexpression of Smad2 significantly increased level of Smad3, P‐Smad3, Smad4 and Foxp3." (PMID 32057179, 2020).
α-synucleinopathies (1 paper, 2011). "Moreover, late onset of α-synucleinopathies in the heterozygous mice when compared with the early onset in the Smad3 null mice suggests that aggregates accumulate in a progressive and gene dosage dependent manner with age." (PMID 21995845, 2011).
tumor (652 papers, 2003 to 2026). "They showed that signaling can change from tumor suppressive to tumor promoting, and that the availability of Smad3-associated cofactors is critical to this transition." (PMID 41109667, 2026). "This stage-specific expression pattern highlights the potential of SMAD3 as a diagnostic tool, warranting further investigation into its regulatory networks and interactions within the tumor microenvironment." (PMID 40361382, 2025). "The PD-1 subpopulation was higher in Smad3-deficient tumor-specific CD8+ TILs, which led to enhanced cytokine production in TILs and draining lymph nodes, resulting in increased anti-tumor activity." (PMID 40432130, 2025). "It was suggested that the inhibition of Smad3 in tumor MO-MDSC was markedly reversed by mutating the m6A site at position 4591, but not 3037, which was restored by administration of STM2457." (PMID 41360769, 2025). "Neutrophils deficient in pro-tumorigenic factors, such as Smad3 or Tollip, have been shown to suppress tumor growth when transferred to tumor-bearing mice." (PMID 40050933, 2025). "From a therapeutic perspective, targeting key molecular drivers of spontaneous neurogenesis—including NGF, GDNF, VEGF, and the TGF-β/Smad3 pathway underlying MNT—represents a promising approach to mitigating the adverse effects of tumor innervation." (PMID 41009819, 2025). "In this study, we demonstrate that marked deficiency of Smad3 is critical for maintaining the immature state of tumor MO-MDSC, acting as an underappreciated regulatory factor that impairs MO-MDSC maturation." (PMID 41360769, 2025). "Expression of collagen genes (e.g., COL1A1 and COL1A2) is induced in tumor stromal cells such as cancer-associated fibroblasts (CAFs) and in tumor cells by transforming growth factor beta 1 (TGFβ1)-mediated phosphorylated SMAD3 (pSMAD3) signaling." (PMID 39574893, 2024). "Mutations in essential pathway components can cause persistent Smad3 linker phosphorylation, so highly phosphorylated Smad3L likely reduces pSmad3C’s sensitivity to growth inhibition in tumor cells." (PMID 38962270, 2024). "In the TGFβ pathway, co-occurring mutations were found in SMAD2 and SMAD3 (FDR-adjusted P = 1.03 × 10−10) in nHM tumours, whereas TGIF1 co-occurred with PIK3CA (FDR-adjusted P = 0.09) in the HM cases." (PMID 39112715, 2024). "By contrast, the adoptive transfer of Smad3-KO-BMDN caused a substantial reduction in tumor growth in association with an even greater increase in total TANs, which exhibited a dominant N1 phenotype." (PMID 37002229, 2023). "The results showed that patients with high tumour expression of SMAD3 were at significantly increased risk of poor response to neoadjuvant chemotherapy." (PMID 37685308, 2023). "The effect of PKCε`s non-synonymous variants (E14K, D39H) on functions of the protein was studied along with the effect of amino acid variants on interactions of PKCε with Smad3 that are responsible for tumor cell growth." (PMID 37667176, 2023). "Patients carrying both high SMAD3 tumour expression and the wild-type rs745103-A allele had an extremely high risk of failing to achieve a complete response (OR:13.45, p = 0.0005)." (PMID 37685308, 2023). "Six genes were up-regulated in the tumor group and high-risk group consisting of SMAD3, CENPA, KIF23, NUSAP1, INCENP, and SMC4." (PMID 36401386, 2022). "SMAD3 has also been shown to be associated with tumor initiation and progression in earlier studies in several cancers." (PMID 36685857, 2022). "We found that not only MNT but also the tumor-associated nocifensive behaviors were largely suppressed in the LLC tumor with Smad3-knockout TME (Smad3-KO mice) in vivo, implying a crucial role of Smad3-dependent TME in the MNT regulation." (PMID 36206343, 2022). "In TGF-β knockout tumor mice and Smad3-deficient mice, the expansion of CD45− EPCs was significantly reduced." (PMID 36567722, 2022).
tumor (continued). "Patients who carried both high SMAD3 tumor expression and the wild-type rs745103-A allele had an extremely high risk of not achieving a complete response (OR:13.45, p = 0.0005)." (PMID 35002714, 2021). "Our most important finding was the identification of some host SMAD3 genetic polymorphisms (rs744910, rs745103) and SMAD3 protein expression in pre-treatment tumor tissue as predictive markers of response to neoadjuvant treatment in LARC." (PMID 35002714, 2021). "In PDAC specimens, SMAD3 upregulation was associated with several features of aggressive disease including a higher tumor grade, lymph node metastasis, increased EMT-like features, and shorter survival." (PMID 34680235, 2021). "The TGF-β/SMAD-3 signaling has been found to be implicated in CRC carcinogenesis with both tumor suppressor effects in the early development of cancer and pro-metastatic effects in late stage disease." (PMID 33916844, 2021). "Patients with high tumor expression of SMAD3 had a significantly increased risk of poor response (TRG≥2) [cellularity >55% (OR:10.36, p = 0.0004), or moderate/high intensity (OR:5.20, p = 0.0038), or an H-score≥1 (OR:9.84, p = 0.0004)]." (PMID 35002714, 2021). "HER2 signaling also directly inhibits canonical TGFβ signaling through phosphorylation of SMAD3 at the S208 site, leading to a loss of the tumor-suppressor function of SMAD3." (PMID 34771508, 2021). "For example, Stephen and associates showed that tumor-derived TGF-β activates Smad3 to increase PD-1 expression by inhibiting the chromatin organizer Satb1 in tumor-reactive T cells." (PMID 34093869, 2021). "The primary aim of the study was to define the association between the constitutive genetic features of SMAD3, tumor protein expression and their combination, and tumor response to standard nCRT regimens in LARC patients." (PMID 35002714, 2021). "The aim was to investigate both host (genetic polymorphisms) and tumor SMAD3 profiling to predict response to nCRT." (PMID 35002714, 2021). "Further analysis of proteomic data revealed that the AGI was strongly correlated with the expression of cell-cycle-related proteins, including pChk1, pChk2, and CyclinB1, and other tumor hallmark proteins, such as eIF4G, pPI3K, Src, Smad1, and Smad3." (PMID 34094917, 2021). "The DNA-binding activity of SMAD3/4 transcription factors complex is inhibited by tumor-derived hepatitis C virus core variants through a direct interaction between the central domain of tumor-derived core and the MH1 DNA-binding domain of SMAD3." (PMID 33546553, 2021). "Ahr-deficient tumours and CPCs grown in vitro, showed elevated activation of the TGFβ mediator, SMAD3." (PMID 31924815, 2020). "Hermes/Rbpms was shown to repress activator protein-1 (AP-1) signaling through cFos, cJun, and Smad3, a pathway implicated in tumor growth and progression." (PMID 26998427, 2016). "An in vivo-weighted TGF-β/Smad3 tumor-suppressor signature was associated with good outcome in estrogen receptor-positive breast cancer cohorts." (PMID 24890385, 2014). "Low ALDH2, high CCNE1 and SMAD3 were significantly associated with increase in tumor depth (T1, T2 and T3; P <0.05, chi-square test)." (PMID 25408144, 2014). "Several studies have shown the tumor suppressor role of Smad3, whose deficiency contributes to tumor formation and development." (PMID 24636138, 2014). "In human cancers, the loss of Smad3 expression has been associated with various malignant carcinomas and is recognized as a tumor suppressor." (PMID 22204491, 2011). "There is strong evidence for tumor suppressor function of SMAD3 as its loss is associated with tumorigenesis in various cancers." (PMID 21835029, 2011).
tumor (continued). "CDK4/cyclin D complexes and other Ras-related kinases modulate the phosphorylation of SMAD3, and this modulation of SMAD3 causes its downstream signaling to change from tumor suppressive to oncogenic." (PMID 20676395, 2010). "Furthermore, bioluminescence imaging and analysis in the intraperitoneal metastasis model confirmed that SMAD3 overexpression rescued the majority of the reduced tumor metastasis and growth caused by NAT10 knockdown." (PMID 41476650, 2025). "Notably, aberrant genomic DNA methylation in NSCLC tumor-associated fibroblasts is a critical regulator of tumor progression, with SMAD3 promoter hypermethylation associated with reduced gene expression." (PMID 38493128, 2024). "The remaining Smad3 or Smad3 wild-type allele is also lost in the late stages of tumor progression." (PMID 38323119, 2024). "Host and tumour SMAD3 status may be considered to improve the risk stratification of LARC patients to facilitate the selection of other personalised neoadjuvant treatment strategies including intensive treatment regimens." (PMID 37685308, 2023). "We demonstrated that pharmaceutical inhibition of Smad3 with the specific inhibitor SIS3 effectively blocked MNT as well as the associated tumor innervation (Tubb3+ and NeuN+ cells) and cancer-associated spontaneous nocifensive behaviors of the LLC-bearing mice." (PMID 36206343, 2022). "To determine whether methylation-deficient mutants of SMAD3 abrogate tumor metastasis in vivo, we injected SMAD3 WT and SMAD3 K53/333R MDA-MB-231 cells into the tail veins of 4-week-old female BALB/c nude mice." (PMID 35085106, 2022). "Smad3 is a pathogenic mediator of TGF-β1 signaling in tumor progression." (PMID 35736633, 2022). "Further, genes associated with the second gene component included SMAD3 which is also a well-known tumor suppressor gene that plays a key role in transforming growth factor β (TGF-β) mediated immune suppression and also in regulating transcriptional responses suitable for metastasis." (PMID 35882830, 2022). "However, we found that EZH2-mediated tumor metastasis markedly abrogated the expression of SMAD3 K53/333R methylation–deficient mutant cells compared with that of WT SMAD3 cells." (PMID 35085106, 2022). "TGF‐β1/Smad3‐dependent transcriptome of BMDM associates with neoplasm formation." (PMID 34791825, 2022). "Host and tumor SMAD3 status might be considered to improve risk stratification of LARC patients to facilitate selection for alternative personalized neoadjuvant strategies including intensified regimens." (PMID 35002714, 2021). "Accordingly, tumor-induced expansion of EPCs is substantially reduced in Smad3-deficient mice." (PMID 33669537, 2021). "The superenhancers contribute to the high expression of tumor-associated genes like Myc and SMAD3." (PMID 34934770, 2021). "Interestingly, SMAD3 hypermethylation in tumours is associated with poorer overall survival (available at Carcinogenesis Online)." (PMID 30624614, 2019). "Additional studies indicated that knockdown of IRS-1 expression prevented the effects of Smad3-deficiency on cell proliferation and apoptosis, indicating that TGFβ/Smad3 mediates tumor suppressor function through the inhibition of IRS-1 expression and activation." (PMID 28414818, 2017). "Several mechanisms may be associated with the promoting effect of Smad3-dependent microenvironment on cancer progression, including angiogenesis, Treg response and tumour-invasive factors, as well as availability of NK cells." (PMID 28262747, 2017). "Because TGF-β signaling occurs during human hepatocellular carcinogenesis and involves a shift in TGF-β/Smad3 function, we speculated that the tumor-suppressive function of IL-37b might be implicated in TGF-β signaling." (PMID 27835881, 2016).